INS (insulin)
Diseases named in the same sentence as INS in open-access papers (continued):
Sharing a sentence is not in itself a finding about the gene and the disease.
Obesity (continued). "It has also been shown that the consumption of a HFD induces an elevation of NK count and the production of pro-inflammatory cytokines in EpiWAT at an early phase of obesity induction, which was linked to increased fasting glucose, insulin levels and ATMs count." (PMID 33282920, 2020). "BS intake might improve metabolic syndromes associated with obesity, by decreasing insulin concentration." (PMID 33207773, 2020). "Higher BAT content and activation, such as by BAT transplantation in mice, positively affects glucose and insulin metabolism and body mass and plays a protective role against obesity pathogenesis and associated metabolic disorders such as hyperglycaemia and hyperlipidaemia." (PMID 32265845, 2020). "Ghrelin is associated with obesity and blood levels of insulin." (PMID 32124259, 2020). "IR was related to increased lung cancer risk, and insulin may also influence obesity-mediated tumors such as renal cancer and ovarian tumor, but the relationship between insulin and ESCC growth had not been examined in the study." (PMID 33381605, 2020). "How increased levels of body fat and obesity, that are frequently associated with alterations in insulin and leptin dependent signaling, influence these signaling networks in the context of melanoma progression is unknown." (PMID 32549336, 2020). "Moreover, due to the unbiased nature that characterizes metabolomic platforms, they can provide a tool to unveil novel underlying mechanisms of insulin resistance, metabolic syndrome and its dire consequences in humans with obesity." (PMID 32523723, 2020). "Also in this perspective, insulin was inversely associated with HRV among patients with higher levels of obesity and lower levels of PA, since the severely obese in the present study showed a low amount of minutes spent on MVPA (98.92 ± 41.00 min/week)." (PMID 32318288, 2020). "Specifically, an increased number of small follicles (<10 mm in diameter) was associated with androgen excess, obesity, and IR, whereas the development of larger (≥10 mm) follicles was linked to improved insulin sensitivity and glucoregulatory status and ovulatory potential." (PMID 32629978, 2020). "The gene-set and pathway analyses revealed five shared pathways, (Wnt signaling pathway, adherens junction, pathways in cancer, axon guidance, and insulin secretion) and seven GO terms to be associated with all evaluated traits, which probably explain that obesity is a polygenic trait." (PMID 33182249, 2020). "Because insulin may support the onset and development of obesity, some researchers suggested the opposite direction, i.e. insulin resistance to mediate the association between nocturnal sleep duration and obesity." (PMID 32603369, 2020). "Therefore, we try to understand the potential interaction between the insulin and ghrelin, both of which are associated with obesity." (PMID 32124259, 2020). "Starting from an early embryonic stage, maternal gut microbiota-SCFA-FFAR2 signaling plays a crucial role in regulating metabolic syndrome, as FFAR2 KO mice embryos have lower insulin and higher glucose level, and are more susceptible to obesity and diabetes in adulthood." (PMID 32521775, 2020). "High II of diet may increase the risk of obesity by stimulating more insulin secretion, which can reduce fat oxidation and increase carbohydrate oxidation, causing an increase in fat storage." (PMID 33008356, 2020). "In addition, dietary proteins containing encrypted bioactive peptides that function to reduce body weight and improve insulin resistance are potential novel therapeutic possibilities for treating or preventing obesity and associated diseases." (PMID 32121443, 2020). "Modern research has elucidated that BBR could regulate gut microbiota to treat obesity, collagen-induced arthritis, periodontal bone loss, and insulin resistance in animal models." (PMID 33072135, 2020).
Obesity (continued). "Deletion of FABP4 increases PPARγ expression, and lipogenesis and insulin sensitivity in adipocytes, suggesting that FABP4-dependent inhibition of PPARγ might favor insulin resistance and induction of inflammatory pathways associated with obesity." (PMID 32856199, 2020). "The result is the impairment of insulin actions and glucose utility in the liver, skeletal muscles, and adipose tissues with a series of metabolic abnormalities, and the eventual development of obesity-associated complications." (PMID 32585823, 2020). "Cohort studies have already revealed that obesity may be associated with the rate of insulin secretion capacity decline." (PMID 32775460, 2020). "Thus, obesity is associated with metabolic abnormalities connected to an increase in circulating levels of insulin and impaired insulin action, as well as to the dysregulation of adipokine secretion (an increase in leptin and decrease in adiponectin levels)." (PMID 32947606, 2020). "Indeed, higher SCD1 and D6D and lower D5D activity have been associated with the impairment of insulin sensitivity in individuals with obesity." (PMID 32486525, 2020). "It was shown that any disorders related to the regulation of these genes may contribute to the development of obesity due to the important role of these genes in hunger regulation (leptin), glucose transport (Glut 4), and insulin susceptibility (adiponectin)." (PMID 32463311, 2020). "Since neuronal LPL deficiency is associated with improved glucose tolerance despite obesity, we reasoned that these animals may be more insulin sensitive." (PMID 32998280, 2020). "Thus, in the absence of Nnat, mice are largely exposed to an energy imbalance the predisposes them to diet‐induced obesity that along with impaired insulin secretion would contribute to the glucose intolerance." (PMID 33089074, 2020). "Intraperitoneal glucose tolerance tests (ipGTT) at the same timepoints showed that there was significant deterioration in glucose tolerance in mice on the HF compared to NC diet (p < 0.0001), which suggested establishment of the insulin resistance associated with the obesity phenotype." (PMID 32678325, 2020). "The normalization of glucose homeostasis, insulin concentration and the reverse obesity in mice with ERα deficiency and removed ovaries, suggests that ERβ may be a base of diabetogenic and adipogenic phenotype." (PMID 32290381, 2020). "Furthermore, evidence suggests that IR, along with the associated hyperglycemia, occurs in classic insulin target organs, and that these conditions are the pathological hallmark of metabolic disorders such as obesity and T2D." (PMID 33905470, 2020). "All these data seem to suggest that insulin sensitivity, as well as glucose uptake into the cell, glycolysis and de novo lipogenesis are decreased in aSAT during obesity but weight loss induced by bariatric surgery corrects these problems or even improves them with respect to controls." (PMID 31941045, 2020). "Compared with the insulin and lipid profiles in the mice fed high-fat diet (HFD), the administration of LPS via subcutaneous infusions into mice could cause the same outcome: increased insulin resistance and obesity." (PMID 33322383, 2020). "In conjunction with changing β‐cell morphology, diabetic‐obesity is associated with altered β‐cell function, including diminished first phase insulin secretion, increased basal insulin secretion, and decreased β‐cell insulin production." (PMID 33113267, 2020). "Additionally, HJV repressor matriptase-2 deficient mice are protected from HFD-induced obesity, showing decreased BMI and improved glucose tolerance and insulin sensitivity." (PMID 32752277, 2020). "As a result of chemokine production by neutrophils, macrophages are recruited into the adipose tissues where they secrete cytokines, such as tumor necrosis factor alpha (TNF-α) and interleukin-1 beta, causing obesity-mediated inflammation and impaired insulin signaling." (PMID 32277104, 2020).
Obesity (continued). "For instance, a higher abundance of Lachnospiraceae has been associated with improved body weight and insulin sensitivity due to a higher production of butyrate and propionate, while others suggested a higher abundance is linked to obesity most likely due to higher acetate production." (PMID 33147768, 2020). "The crosstalk between MAPK/ERK and Akt-mTOR signaling in adipocytes may predict an increasing risk of obesity related to adipogenesis/lipogenesis, insulin resistance and production of inflammatory cytokines." (PMID 30621146, 2019). "The increased insulin sensitivity was associated partly with having lower visceral fat (49% less) and an earlier age-related onset of obesity compared with those with metabolically normal obesity." (PMID 31652553, 2019). "In addition to the significant differences observed in serum adipokines, fasting glucose levels, insulin levels, and glucose tolerance, obesity was also associated with elevated serum levels of IGF-1, IGF-1/IGFBP2, and IGF-1/IGFBP3 in HFD-Obese mice." (PMID 30867005, 2019). "This study provided some novel insights into the pathways involved in mediating the risk increase in RCC that is caused by obesity, most notably through insulin and DBP, but further research is needed to fully elucidate the important relationship between obesity and RCC." (PMID 30605491, 2019). "Of note, catestatin suppressed hepatic glucose production and was associated with improved insulin sensitivity in mice with diet-induced obesity, while it also induced glucose uptake and GLUT4 trafficking in adult rat cardiomyocytes, thus, likely improving cardiac energetics." (PMID 31366074, 2019). "Altered glucose tolerance in children and adolescents with obesity is associated with greater resistance to insulin in adipose tissue, yet the relation of adipose insulin sensitivity, independent of whole-body insulin sensitivity, and the degree of obesity in the pediatric age group are less clear." (PMID 30637483, 2019). "Dysregulation of a number of pathways has been hypothesized to mechanistically link obesity with increased risk of breast cancer recurrence in humans, including changes in circulating adipokines, insulin/IGF-1, sex hormones, and chronic inflammation." (PMID 30867005, 2019). "Additionally, some pathological mechanisms were related to this problem, such as deficiency or disorder of insulin, obesity, sexual hormone disturbance, and diabetic complications." (PMID 31497541, 2019). "Early studies described the presence of conventional DCs (cDCs) in adipose tissues, and depletion of these cells has been shown to result in a rapid normalization of insulin sensitivity and a decrease in proinflammatory cytokines in obese mice, suggesting a pathogenic role for cDCs in obesity." (PMID 31191541, 2019). "Moreover, iNOS exhibits a pathogenic role in obesity-associated β-cell dysfunction and damage, inhibiting the glucose-stimulated secretion of insulin." (PMID 31500090, 2019). "Taken together, accumulated evidence suggest SUA levels may be associated with insulin secretion in T2DM patients with overweight/obesity." (PMID 30941277, 2019). "Though adult β cells are largely in a quiescent state (evidenced by a very low frequency of proliferation), β cell mass demonstrates a degree of plasticity, expanding in response to metabolic demands associated with the insulin resistance of pregnancy and obesity." (PMID 31401713, 2019). "Therefore, there is a strong need to investigate alternative insulin-lowering therapies as a potential adjunct in those with obesity-associated tumors." (PMID 31867105, 2019). "Individuals with obesity show characteristic imbalance of metabolic profile which is associated with profound changes in insulin sensitivity, inflammatory reaction and other biochemical metabolites alterations, making an individual more potential to metabolic disorders." (PMID 30679939, 2019).
Obesity (continued). "The distinct physiological roles of these macrophage phenotypes are reflected in the pathogenesis of obesity which is associated with increased adipose tissue M1 macrophage infiltration and release of inflammatory cytokines leading to antagonism of insulin signaling." (PMID 30553769, 2019). "Whilst the existence of as yet unidentified factors controlling body weight and metabolism should be noted, what we do know so far is that, except for adiponectin, circulating concentrations of these hormones are increased in obesity and insulin-resistant states, and decrease after weight-loss." (PMID 31608010, 2019). "Interestingly, it has been shown that the effect of insulin in the brain is completely lost in the case of obesity and is restored with weight loss." (PMID 31143098, 2019). "Hyperinsulinemia has emerged as a focal point of research on obesity-related tumors, with increased plasma insulin concentrations independently predicting increased risk and mortality in prostate, colon, breast, endometrial, and pancreatic cancer, as well as several other tumor types." (PMID 31188872, 2019). "Obesity is a risk factor for the development of hypertension, which can increase hypertension through multiple mechanisms, including insulin resistance, activation of sympathetic nervous system, sodium retention leading to increased renal reabsorption and activation of the renin–angiotensin system." (PMID 30828463, 2019). "Also, circulatory 2-AAA was positively associated with obesity-related factors (fat mass, fat percent, waist circumference, BMI, BMI z-score, triglycerides, insulin, and HOMA-IR) at baseline and after 2 years in the children cohort study." (PMID 31541119, 2019). "Taken together, these data demonstrate that hyperinsulinemia per se promotes both breast and colon cancer progression in obese mice, and highlight SGLT2 inhibitors as a clinically available means of slowing obesity-associated tumor growth due to their glucose- and insulin-lowering effects." (PMID 31867105, 2019). "Several theories have been postulated to explain these obesity-associated cardiac abnormalities, such as alterations in myocardial substrate utilization, mitochondrial dysfunction, neurohormonal dysfunction, leptin resistance, and impaired insulin signaling." (PMID 31379826, 2019). "We, and others, have also previously demonstrated that obesity in rodents and chronic oversupply of metabolic fuel to skeletal muscle cells in vitro is associated with an increase in proinflammatory NFkB signalling and insulin resistance." (PMID 31101940, 2019). "Whereas overweight/obesity is thought to increase ER-positive cancer through peripheral aromatization of estrogens by adipose tissue and through insulin signaling, our finding of increased ER-positive risk in normal/underweight women with dense breasts merits further investigation." (PMID 30944014, 2019). "This would be in concert with epidemiologic studies drawing attention to increasing ratios of omega-6 to omega-3 in the American diet over time and associations with obesity, as well as benefits to insulin sensitivity with supplementation of omega-3 fatty acids." (PMID 31984379, 2019). "By applying k-means and hierarchical clustering algorithms, they identified five reproducible subgroups of patients: a severe autoimmune form (capturing T1D and LADA), a severe insulin-deficient form, severe insulin-resistant form, mild obesity-related form, and mild age-related form." (PMID 31292748, 2019). "A previous study has demonstrated that WFA improves insulin sensitivity and promotes weight loss by acting as a leptin sensitizer, while the present study investigated further the insulin sensitizing and anti-obesity effects of WFA." (PMID 31226166, 2019). "The present study highlighted the fact that vitamin D might be associated with an improvement in both insulin sensitivity and effectiveness, and with a decrease in fat mass and obesity in rats with PCOS." (PMID 31673465, 2019).
Obesity (continued). "Obesity in humans is frequently associated with impaired insulin sensitivity." (PMID 30867005, 2019). "Recent studies have demonstrated that saturated fats and animal protein, which are typically high in a Western diet, are associated with metabolic disorders such as obesity, reduced insulin sensitivity, T2D, and CVD, and also altered microbiota, e.g., reduced diversity." (PMID 30046942, 2019). "In light of these and previous data, it is unlikely that vitamin D supplementation improves obesity or cardiovascular risk factors but might even have a potential harmful effect on obesity and insulin sensitivity." (PMID 31416155, 2019). "Whilst perirenal adipose tissue signalling demonstrated an increase in insulin signalling mRNA expression associated with exposure to maternal obesity during gestation, gonadal adipose tissue demonstrated the opposite effect, highlighting a difference between the two depots." (PMID 31300679, 2019). "The decrease in %-LF is associated with decrease in blood lipids (total cholesterol and LDL) and plasma insulin after surgery, and the decrease in VAT is associated with changes in insulin, indicating a clear improvement in obesity-associated metabolic risk factors." (PMID 31089967, 2019). "These salivary biomarkers correspond well to the established circulating plasma biomarkers associated with obesity, reflecting the metabolic aspect (e.g., insulin and leptin) as well as the inflammatory aspect (e.g., CRP and adiponectin) of the mechanism underlying obesity." (PMID 31236292, 2019). "Finally, C57BL/6 strain also displays severe phenotype of diet-induced NAFLD/NASH associated liver injury, obesity, glucose intolerance, and insulin response through genetic or epigenetic mechanisms compared to BALB/C54,55." (PMID 31844325, 2019). "Furthermore, chronic low-grade inflammation caused by obesity, as well as ROS, leads to reduced insulin sensitivity of the cells, resulting in IR." (PMID 31212845, 2019). "These associations and possible mechanisms of the deficiencies' metabolic effects, such as their influence on leptin and insulin metabolism, need further studies to help clarify the roles of the different micronutrient deficiencies with respect to obesity and its comorbid conditions." (PMID 31598578, 2019). "CYP2E1 expression has been reported to be inhibited by insulin, and to be associated with obesity." (PMID 31031804, 2019). "Dapagliflozin slows tumor growth in two mouse models (E0771 breast cancer and MC38 colon adenocarcinoma) of obesity-associated cancers in vivo, and a mechanistically different insulin-lowering agent, CRMP, also slowed breast tumor growth through its effect to reverse hyperinsulinemia." (PMID 31867105, 2019). "Overall, our findings indicate that physical exercise may act as a non-pharmacologic method that protects against cognitive dysfunction caused by obesity by improving hippocampal insulin signaling and neuroplasticity." (PMID 31311133, 2019). "Obesity is frequently associated with high glucose levels and endoplasmic reticulum stress with increased release of reactive oxygen and reactive nitrogen species, impairing insulin secretion, and insulin sensitivity." (PMID 31467596, 2019). "Indeed, DNA methylation has been associated with insulin sensitivity, coronary heart disease, obesity, and breast cancer." (PMID 30003100, 2018). "We assessed whether macronutrients and food groups are longitudinally associated with insulin sensitivity and secretion over a 2-y period in children with a family history of obesity, and whether associations differ by level of adiposity." (PMID 30383280, 2018). "Collectively, systemic oxidative stress-associated HFD and obesity may lead to insulin sensitivity of metabolic organs, which thus promotes the inflammatory response." (PMID 29643982, 2018).